RN7SL594P (RNA, 7SL, cytoplasmic 594, pseudogene)
Gene: Miscellaneous RNA gene on chromosome 20 (25,654,595 to 25,654,881, reverse strand). Ensembl gene ENSG00000242236.
Homologues: Orthologues: chimpanzee Metazoa_SRP (100% identical). Paralogues in human: RN7SL296P (75% identical), RN7SL1 (74% identical), RN7SL3 (74% identical), RN7SL679P (73% identical), RN7SL126P (73% identical), RN7SL145P (73% identical), RN7SL2 (73% identical), RN7SL322P (73% identical), RN7SL375P (72% identical), RN7SL408P (72% identical), RN7SL44P (72% identical), RN7SL660P (72% identical), and 698 more.